KCTD10 (potassium channel tetramerization domain containing 10)
Description:
Substrate-specific adapter of a BCR (BTB-CUL3-RBX1) E3 ubiquitin ligase complex that mediates the ubiquitination of multiple substrates, leading to either their proteasomal or lysosomal degradation, or modulating their activity through non-degradative ubiquitination. Controls endothelial barrier function by mediating 'Lys-63'-linked polyubiquitination of RHOB, promoting its lysosomal degradation. Mediates polyubiquitination of CEP97, targeting it for proteasomal degradation. CEP97 degradation upon serum starvation is essential for primary cilium formation by enabling removal of the CEP97-CP110 complex from mother centrioles. Acts as a positive regulator of ferroptosis by destabilizing SLC7A11. Decreased SLC7A11 levels reduce cystine uptake and glutathione (GSH) biosynthesis, thereby promoting iron-dependent lipid peroxidation and ferroptotic cell death. In the innate immune response, mediates 'Lys-27'-linked polyubiquitination of TICAM1/TRIF at Lys-523 upon stimulation with LPS. This ubiquitination is essential for recruitment of TICAM1 to TLR3/4, thereby promoting TLR3/4-mediated immune signaling. Negatively regulates KCTD13 stability through the ubiquitin/proteasome degradation pathway within the developing brain to control neuronal progenitor cell proliferation and differentiation (By similarity). Acts as a sensor for co-directional transcription-replication conflicts, where it helps coordinate the interaction between the replication machinery and RNA polymerase to allow DNA replication to continue through actively transcribed regions. Promotes recruitment of ubiquitin ligase complexes that remove stalled transcription factors, thereby maintaining genome stability by resolving these conflicts. Ubiquitinates TCEA2 to remodel the RNAP complex.
Synonyms: hBACURD3; MSTP028; BTBD28; ULRO61
Tractability: Antibody: its Gene Ontology location is reachable by antibodies, with high confidence. PROTAC: ubiquitination databases record sites on it; its protein half-life has been measured.
Gene: Protein-coding gene on chromosome 12 (109,448,655 to 109,477,359, reverse strand). Ensembl gene ENSG00000110906.
Subcellular location: Nucleus
Subcellular location (Human Protein Atlas): Nucleoplasm; Cytosol
Gene Ontology:
Molecular function: identical protein binding; Notch binding; protein binding; ubiquitin-like ligase-substrate adaptor activity; ubiquitin-protein transferase activity
Biological process: cilium assembly; establishment of endothelial barrier; positive regulation of cilium assembly; positive regulation of ferroptosis; positive regulation of protein K63-linked ubiquitination; proteasome-mediated ubiquitin-dependent protein catabolic process; ubiquitin-dependent protein catabolic process; negative regulation of Rho protein signal transduction; protein ubiquitination; protein homooligomerization
Cellular component: cytoplasm; nucleoplasm; Cul3-RING ubiquitin ligase complex; MKS complex; nucleus
Genetic constraint (gnomAD): Loss-of-function variants: 13 observed, 36.19 expected, observed/expected ratio (o/e) 0.36, 90% interval 0.23 to 0.57. The upper end of that interval is the gene's LOEUF score, 0.57, which puts it in group 2 of 6, group 1 being the genes least tolerant of losing a copy. Missense variants: 256 observed, 439.37 expected, observed/expected ratio (o/e) 0.58, 90% interval 0.52 to 0.65. Synonymous variants: 156 observed, 178.14 expected, observed/expected ratio (o/e) 0.88, 90% interval 0.77 to 1.
Homologues: Orthologues: chimpanzee KCTD10 (100% identical), dog KCTD10 (100% identical), pig KCTD10 (100% identical), macaque KCTD10 (99% identical), rabbit KCTD10 (99% identical), guinea pig KCTD10 (98% identical), mouse Kctd10 (98% identical), rat Kctd10 (98% identical), tropical clawed frog kctd10 (96% identical), zebrafish kctd10 (95% identical), Drosophila melanogaster CG10465 (61% identical), Caenorhabditis elegans D2045.8 (29% identical), and 28 more. Paralogues in human: TNFAIP1 (71% identical), KCTD13 (69% identical).
Diseases named in the same sentence as KCTD10 in open-access papers:
KCTD10 is named in the same sentence as 37 diseases in open-access papers, as found by Europe PMC text mining. Sharing a sentence is not in itself a finding about the gene and the disease. The quoted sentences say what the papers report.
breast carcinoma (6 papers, 2021 to 2025). "Our result indicated that the depletion of CUL3 or KCTD10 caused the accumulation of RhoB protein in HER2-positive breast cancer cells." (PMID 34187934, 2021). "In breast cancer, decreased cystine levels in the tumor microenvironment remodel the expression of KCTD10 and USP18, regulating SLC7A11 stability and subsequently cystine metabolism." (PMID 41330917, 2025). "Biologically, USP18 knockdown suppresses, whereas KCTD10 knockdown promotes growth of breast cancer cells via reducing or increasing SLC7A11, respectively." (PMID 40440083, 2024). "Here, we showed that KCTD10 knockdown increased the viability and clonogenic survival of breast cancer cells by stabilizing SLC7A11 to confer resistance to ferroptosis, which was abrogated by either SLC7A11 knockdown or treatment with a ferroptosis inducer." (PMID 38959043, 2024). "Consistently, the high levels of SLC7A11 and USP18, and low levels of KCTD10 are coordinately coupled with decreased cystine levels in breast cancer tissues, indicating the pathological relevance." (PMID 38959043, 2024). "Compared to normal tissues, expression of SLC7A11 and USP18 was increased, whereas expression of KCTD10 was decreased in multiple types of human cancers, including breast cancer." (PMID 38959043, 2024). "We previously reported that the constitutive degradation of an endosomal small GTPase RhoB by the CUL3/KCTD10 E3 complex functions in EGF-induced Rac1 activation specifically in HER2-positive breast cancer cell lines, among other breast cancer subtypes." (PMID 34187934, 2021). "Taken together, it is likely that the regulation of EGFR phosphorylation through PTPRH activation and RhoB degradation by the CUL3/KCTD10 E3 complex is conserved in HER2/EGFR-double positive breast cancer cells." (PMID 34187934, 2021). "It is likely that expression of CUL3 and KCTD10 would be reduced by microRNAs also in HER2-positive breast cancer cells under specific patho-physiological conditions." (PMID 34187934, 2021). "In HER2‐positive breast cancers, one of the most aggressive subtypes of breast cancer, KCTD10 induces RhoB degradation and activation of Rac1, which promotes progression of tumors, and resistance to therapy." (PMID 34001146, 2021). "Thus, KCTD10 suppressed the survival of breast cancer cells by promoting ubiquitylation and degradation of SLC7A11 to induce ferroptosis." (PMID 38959043, 2024). "Our correlation study using the human breast cancer tissues also revealed a negative association between KCTD10 and SLC7A11, and a positive association between USP10 and SLC7A11 at both mRNA and protein levels, indicating a pathological relevance of our finding." (PMID 38959043, 2024). "In clinical breast cancer samples, we found elevated levels of SLC7A11 and USP18, and reduced levels of KCTD10." (PMID 40440083, 2024). "Collectively, KCTD10 has growth-suppressive, while USP18 has growth-promoting role in breast cancer cells." (PMID 38959043, 2024). "Biologically, KCTD10 and USP18 confer breast cancer cells’ sensitivity or resistance to ferroptosis, respectively, via targeting SLC7A11." (PMID 38959043, 2024). "To examine the roles of the CUL3/KCTD10 complex in the activation of EGFR and HER2, we first examined the phosphorylation of those receptors in HER2-positive breast cancer cells." (PMID 34187934, 2021). "For HER2/EGFR double-positive breast cancer cells, our present study suggests that RhoB functions as a tumor suppressor because its constitutive degradation by the CUL3/KCTD10 E3 complex is essential for cell proliferation of SKBR-3 cells." (PMID 34187934, 2021). "Here, we report that degradation of an endosomal small GTPase, RhoB, by the ubiquitin ligase complex cullin-3 (CUL3)/KCTD10 is essential for both EGFR and HER2 phosphorylation in HER2-positive breast cancer cells." (PMID 34187934, 2021).
breast carcinoma (continued). "In this study, we found that depletion of CUL3 or KCTD10 reduced the phosphorylation of EGFR and HER2, as well as cell proliferation of HER2-positive breast cancer cells." (PMID 34187934, 2021). "Thus, in contrast to KCTD10, USP18 promotes the survival of breast cancer cells by stabilizing SLC7A11 to suppress ferroptosis." (PMID 38959043, 2024). "In breast cancer tissues with reduced cystine abundance, a negative correlation between KCTD10 and SLC7A11 and a positive correlation between USP18 and SLC7A11 were observed, respectively." (PMID 38959043, 2024). "Under either cystine-enriched or cystine-starved condition, SLC7A11 knockdown inhibited, whereas KCTD10 knockdown promoted cell viability and clonogenic survival, suggesting that SLC7A11 promotes cell viability and survival, whereas KCTD10 inhibits them in breast cancer cells." (PMID 38959043, 2024). "Finally, we performed biological assays to determine whether KCTD10 or USP18 coordinates with SLC7A11 to regulate the cell viability and clonogenic survival of breast cancer cells." (PMID 38959043, 2024). "The IHC staining of human breast cancer tissues showed that in general, the SLC7A11 levels were positively correlated with USP18 levels, but negatively correlated with the KCTD10 levels in both nontumor and tumor tissues." (PMID 38959043, 2024).
gastrointestinal stromal tumor (4 papers, 2014 to 2025). "KCTD10 has also been linked to the development of certain, including gastrointestinal stromal tumor (GIST) and pancreatic cancer." (PMID 40873559, 2025). "There has even been a novel transcription factor ETV1 identified, which is unique to gastrointestinal stromal tumors (GISTs), suggesting that KCTD10 functions as a tumor suppressor protein." (PMID 31583032, 2019). "A recent study revealed KCTD10 as a novel prognostic biomarker in gastrointestinal stromal tumor." (PMID 27716295, 2016). "In a recent study, KCTD10 was reported to be regulated by a novel transcription factor ETV1 which is unique to gastrointestinal stromal tumors (GISTs), and RNAi-mediated silencing of KCTD10 increased cell invasion, suggesting that KCTD10 function as a tumor suppressor protein." (PMID 25401743, 2014).
lung carcinoma (4 papers, 2013 to 2025). "High KCTD10 expression was associated with prolonged overall and post-progression survival in lung cancer patients, indicating the potential clinical significance of KCTD10 in lung cancer diagnosis, treatment and prognosis." (PMID 40873559, 2025). "KCTD10 has been implicated in malignant phenotypes of several tumors, but the role of KCTD10 in lung cancer remains largely unexplored." (PMID 40873559, 2025). "Thus, KCTD10 expression is inversely correlated with lung cancer stage and is associated with a favorable prognosis for lung cancer patients." (PMID 40873559, 2025). "Kaplan-Meier Plotter survival analysis revealed that high KCTD10 expression significantly correlated with improved prognosis in lung cancer patients with CD8+ T cell infiltration, indicating a potential role in immune system activation." (PMID 40873559, 2025). "Our study revealed that endothelial Kctd10 knockout in mice accelerates lung cancer progression and tumor angiogenesis." (PMID 40873559, 2025). "Western blots further confirmed reduced KCTD10 expression in lung cancer cell lines compared with bronchial epithelial Bears-2b cells." (PMID 40873559, 2025). "To further investigate the functional role of KCTD10, we constructed a stable A549 lung cancer cell line overexpressing KCTD10 by lentiviral transduction and demonstrated successful overexpression of KCTD10 by fluorescence imaging and Western blots." (PMID 40873559, 2025). "Although KCTD10 has been reported to interact with PCNA in A549 lung cancer cells, its precise function and molecular mechanisms in lung cancer are elusive." (PMID 40873559, 2025). "IHC analysis revealed that KCTD10 expression was markedly lower in high-stage lung cancer patients, with a particularly pronounced reduction in LUAD." (PMID 40873559, 2025). "To investigate the upstream regulatory mechanism of KCTD10 expression in lung cancer, we explored the m6A modification, the most common form of mRNA modification for the regulation of mRNA stability." (PMID 40873559, 2025). "Both METTL14 and YTHDF2 exhibit low expression in lung cancer but are positively correlated with better patient prognosis, suggesting that impaired METTLE14-YTHDF2 activity contributes to the downregulation of KCTD10 in lung cancer." (PMID 40873559, 2025). "In conclusion, KCTD10 suppresses lung cancer metastasis and tumor angiogenesis by interacting with β-catenin to promote its ubiquitin-dependent degradation, which then inhibits EMT and PD-L1 expression, leading to the improving outcome of anti-PD-1 therapy." (PMID 40873559, 2025). "To determine the molecular mechanism of KCTD10 in lung cancer, we performed IP followed by silver staining and MS." (PMID 40873559, 2025). "The METTL14-YTHDF2 axis enhances KCTD10 mRNA stability via m6A modification, clarifying the regulatory mechanisms of low KCTD10 expression in lung cancer." (PMID 40873559, 2025). "Taken together, KCTD10 suppresses lung cancer progression and immune escape via the β-catenin/PD-L1 axis, and its expression is tightly regulated by METTL14-dependent m6A modification, highlighting its potential as a therapeutic target." (PMID 41164187, 2025). "IHC analysis further confirmed that KCTD10 expression negatively correlates with the pathologic stage of lung cancer." (PMID 40873559, 2025). "The dual role of KCTD10 in tumor cells and the tumor microenvironment was demonstrated through lung cancer mouse models and conditional Kctd10 knockout studies." (PMID 40873559, 2025). "High KCTD10 expression levels have also been detected in lymphoblastic leukemia, Burkitt’s lymphoma, colorectal adenocarcinoma, lung carcinoma and melanoma tumor lines; nevertheless, the KCTD10 involvement in these tumors has yet to be investigated in detail." (PMID 34001146, 2021). "A previous study has shown that KCTD10 interacts with proliferating cell nuclear antigen, and increases DNA synthesis and proliferation of lung cancer cells." (PMID 23977394, 2013).
lung carcinoma (continued). "Importantly, overexpression of KCTD10 reduced β-catenin and its downstream effector, PD-L1, in lung cancer cells." (PMID 40873559, 2025). "In this study, we identified low KCTD10 expression in lung cancer from the GEPIA database." (PMID 40873559, 2025). "To determine whether KCTD10 influences metastatic ability of lung cancer, we performed wound healing, cell migration and invasion assays and found that KCTD10 overexpression significantly inhibited the migration and invasion ability of A549 cells." (PMID 40873559, 2025). "In this study, we demonstrated that KCTD10 suppresses lung cancer proliferation and metastasis by promoting β-catenin degradation, leading to decreasing PD-L1 expression and enhanced efficacy of anti-PD-1 immunotherapy in lung cancer and lung cancer brain metastases." (PMID 40873559, 2025). "In this study, we found that KCTD10 expression is significantly reduced in lung cancer tissues, and overexpression of KCTD10 could inhibit lung cancer progression both in vitro and in vivo." (PMID 40873559, 2025). "Interestingly, the hazard ratio (HR) for KCTD10 was lower in LUAD, implying a notable role for KCTD10 in this lung cancer type." (PMID 40873559, 2025). "Importantly, combined KCTD10 overexpression and PD-1 blockade exhibited a pronounced synergistic effect in suppressing lung cancer progression and brain metastasis." (PMID 41164187, 2025). "In addition, vascular endothelial cell-specific knockout of Kctd10 (Kctd10flox/floxCDH5CreERT2/+) promoted lung cancer metastasis and tumor angiogenesis through β-catenin signaling." (PMID 40873559, 2025). "Rational drug design aimed at developing specific KCTD10 activators may represent a novel and effective strategy for lung cancer treatment." (PMID 40873559, 2025). "KCTD10 has been reported to play different roles in several tumors, but its mechanism in lung cancer remains unclear." (PMID 40873559, 2025). "Notably, the combined treatment of KCTD10 overexpression with anti-PD-1 antibodies exhibited a synergistic effect in suppressing lung cancer progression and brain metastatic colonization in mice." (PMID 40873559, 2025). "Since KCTD10 downregulates β-catenin and PD-L1, and PD-L1 expression is known to promote tumor immune evasion in lung cancer, we investigated the impact of KCTD10 on lung cancer immunotherapy." (PMID 40873559, 2025). "Furthermore, endothelial-specific knockout of Kctd10 promotes lung cancer metastasis and angiogenesis." (PMID 40873559, 2025). "To assess the expression of KCTD10 in lung cancer, we analyzed the TCGA Pan-Cancer and GEPIA database and found lower KCTD10 expression in lung cancer tissues than in normal tissues." (PMID 40873559, 2025). "Our findings establish KCTD10 as a critical regulator of both tumor progression and the tumor environment, highlighting the therapeutic potential of the novel METTL14/KCTD10/β-catenin regulatory axis in lung cancer treatment." (PMID 40873559, 2025). "However, the current study did not extensively dissect the role of KCTD10 between immune activation in specific lung cancer subtypes and immune cell subsets, including regulatory T cells (Tregs)." (PMID 40873559, 2025).
atherosclerosis (3 papers, 2016 to 2026). A disease characterized by the build-up of fatty material and calcium deposition in the arterial wall resulting in partial or complete occlusion of the arterial lumen. "KCTD10 has been linked to obesity, diabetes, and atherosclerosis." (PMID 36381427, 2022). "KCTD10, which is close to MVK and MMAB genes, has shown to contribute to the susceptibility of obesity, diabetes and atherosclerosis." (PMID 27716295, 2016). "Our results unveil a VSMC-specific atheroprotective role for KIF13B, define the KIF13B/KCTD10/KLF4 pathway as a key regulatory axis governing VSMC fate and plaque stability, and validate the therapeutic potential of KIF13B for treating advanced atherosclerosis." (PMID 41609725, 2026).
Obesity (3 papers, 2016 to 2022). Accumulation of substantial excess body fat. "Evaluated genotypes also included those relating to cardiovascular health (ACE), obesity and metabolism-related genotypes (FTO, UCP1, MC4R, and ADIPOQ), sweet taste perception (Tas1R2 and KCTD10), and endurance (GDF5)." (PMID 36235756, 2022).
autism (2 papers, 2022 to 2025). Persistent deficits in social interaction and communication and interaction as well as a markedly restricted repertoire of activity and interest as well as repetitive patterns of behavior. "Our predictions highlight the peculiar oligomerization properties of the members of Cluster 6 (KCTD10, KCTD13, and TNFAIP1), which are involved in important neurological pathologies including autism." (PMID 36362127, 2022).
coronary artery disease (2 papers, 2016 to 2023). "This SNP is intronic to KCTD10, which has previously been identified in GWAS of neurotic disorder, well-being, coronary artery disease, and HDL cholesterol levels." (PMID 37770476, 2023). "This study aimed to evaluate the associations between functional polymorphisms in three genes (MVK, MMAB and KCTD10) and HDL-C concentrations, as well as coronary heart disease (CHD) susceptibility in Chinese individuals." (PMID 27716295, 2016).
diabetic retinopathy (2 papers, 2022 to 2025). "Knockdown of KCTD10 reduces VEGF secretion and affects angiogenesis in diabetic retinopathy, suggesting that KCTD10 interferes with angiogenesis in both physiologic and pathologic angiogenic processes." (PMID 40873559, 2025). "We purposed to evaluate the KCTD10 effects of angiogenesis in diabetic retinopathy (DR)." (PMID 36381427, 2022).